MAP1B (microtubule associated protein 1B)
Diseases named in the same sentence as MAP1B in open-access papers (continued):
Sharing a sentence is not in itself a finding about the gene and the disease.
neuroblastoma (3 papers, 2012 to 2024). Neuroblastoma (NB) is the most common solid, extracranial childhood tumor. "Furthermore, co-immunoprecipitation assays in SH-SY5Y neuroblastoma cells and the rat brain suggest full length of both 5-HT6Rs and MAP1B interact with each other in native tissues." (PMID 24614691, 2014). "The results obtained in neuroblastoma cells support that endogenous MAP1B heavy and light chain 1, can assemble a protein complex with expressed myc-HC and myc-LC1 construct, making not possible to distinguish the real contribution for each fragment toward Rac1 activity." (PMID 23300879, 2012). "We then tested the interaction in human neuroblastoma SH-SY5Y cells, which express MAP1B endogenously." (PMID 24614691, 2014). "We expressed each MAP1B construct (FL, HC, and LC1) in neuroblastoma N1E115 cells, and measured the activity of Rac1." (PMID 23300879, 2012). "In contrast, Tiam1 was immunoprecipitated by all three MAP1B constructs (FL, HC and LC1) in neuroblastoma cells." (PMID 23300879, 2012). "MAP1B was also highly expressed at the protein level in TNBC cell lines and neuroblastoma SH-SY5Y cells but not in non-TNBC cell lines (MAP1B-HC, and -LC1)." (PMID 38353696, 2024).
schizophrenia (3 papers, 2023 to 2024). A major psychotic disorder characterized by abnormalities in the perception or expression of reality. "To investigate this hypothesis, we determined miRNA expression in microtubule associated protein 1B (MAP1B)–enriched serum EVs derived from neurons from a large cohort of individuals with schizophrenia and nonpsychiatric comparison participants." (PMID 38019909, 2023).
bladder cancer (2 papers, 2022 to 2023). "Collectively, these results supported the idea that the MAP1A/miR-34a-5p/LINC0667/circ_MYLK/circ_MAP1B ceRNA network may play a role in the pathological processes of bladder cancer." (PMID 36408130, 2022). "Five genes in our prognostic model, ANXA1, MAP1B and SPOCD1 have been reported in bladder cancer, however DOK7 and FKBP10 has not been studied in bladder cancer." (PMID 36709279, 2023).
brain tumors (2 papers, 2021 to 2025). "Dysregulated MAP1B expression has been reported in breast, colorectal, and brain tumors, where it promotes proliferation, invasion, and therapeutic resistance." (PMID 41208987, 2025).
deafness (2 papers, 2020 to 2023). An inherited or acquired condition characterized by the complete loss of the ability to hear from one or both ears. "Using the whole exome sequencing approach, in combination with functional assays and a mouse disease model, we identified the potentially novel deafness-causative MAP1B gene encoding a highly conserved microtubule-associated protein." (PMID 33268592, 2020). "Using the WES approach, in combination with functional assays and an animal disease model, we identified the potentially novel deafness-causative MAP1B gene encoding a highly conserved microtubule-associated protein." (PMID 33268592, 2020). "These were further supported by the observations that MAP1B deficiency did not affect the morphologies in middle turns, apex, and basal turns of cochlea of mice, in contrast with those in mice bearing other deafness-causing gene mutations such as CDC14A." (PMID 33268592, 2020).
developmental delay (2 papers, 2018 to 2023). "The cg20997359-associated gene MAP1B was found to be associated with global developmental delays, seizures, and dysmorphic features due to a MAP1B non-sense mutation in a case study." (PMID 38249614, 2023). "Copy number variations spanning MAP1B have also been reported in individuals where the most frequently described trait is ID or developmental delay." (PMID 30150678, 2018).
fragile X syndrome (2 papers, 2012 to 2015). A genetic syndrome caused by mutations in the FMR1 gene which is responsible for the expression of the fragile X mental retardation 1 protein. "Further, MAP-1B is overexpressed in Fragile X syndrome, in which spines are significantly elongated." (PMID 22482073, 2012). "Furthermore, MAP1B is overexpressed in Fragile X syndrome, in which spines are elongated." (PMID 22482073, 2012).
glioma (2 papers, 2025). A benign or malignant brain and spinal cord tumor that arises from glial cells (astrocytes, oligodendrocytes, ependymal cells). "Consistently, the hyperphosphorylation of microtubule‐associated proteins (MAP2 and MAP1B) revealed the activation of CAMK2G, GSK3A, GSK3B, MAPK8, and MAP4K6, corresponding to the active MAPK signaling pathway in glioma." (PMID 39716938, 2025). "The markers for this population are largely expressed only in glioma cells (e.g., NFIB, MAP1B, TUBB2B) and they express low levels or have no expression of myeloid/immune markers (CD74, APOE, HLA genes, and CD45)." (PMID 40588233, 2025).
insomnia (2 papers, 2020 to 2023). A sleep disorder characterized by difficulty in falling asleep and/or remaining asleep. "KEGG and GO analyses enrichment for four nerve–related proteins with differential levels in the warm acupuncture treated group were Prolargin, NMDA receptor synaptonuclear-signaling and neuronal migration factor, transmembrane protein 41B and Microtubule-associated protein 1B to adjust insomnia." (PMID 32249904, 2020).
osteosarcoma (2 papers, 2014 to 2018). A usually aggressive malignant bone-forming mesenchymal neoplasm, predominantly affecting adolescents and young adults. "In contrast, when osteosarcoma cells express a constitutively activated Rac1 protein, the downregulation of MAP1B causes a strong increase in the percentage of fast comets, analogous to our observations in large growth cones." (PMID 30065631, 2018).
polymicrogyria (2 papers, 2021 to 2025). A developmental brain abnormality characterized by an excessive amount of small convolutions on the surface of the brain and cognitive dysfunction. "Notably, mutation of the Tubb2b and Map1b genes have been implicated in polymicrogyria in the cerebral cortex." (PMID 34588434, 2021).
Stroke (2 papers, 2014 to 2022). Sudden impairment of blood flow to a part of the brain due to occlusion or rupture of an artery to the brain. "We confirm this strong influence of post-stroke training (both voluntary and FAU) on basal neuronal plasticity mechanisms, and find up regulation of NTRK2, NMDA 2a receptor, or MAP1b." (PMID 24528872, 2014).
age-related macular degeneration (1 paper, 2023). Age-related loss of vision in the central portion of the retina (macula), secondary to retinal degeneration. "ADAMTS genes (ADAMTS1, ADAMTS6 and ADAMTS9) may associate with age-related macular degeneration and MAP1B was higher expression in the macula of human eye." (PMID 37389979, 2023).
Autoimmunity (1 paper, 2023). The occurrence of an immune reaction against the organism's own cells or tissues. "Microtubule-associated protein 1B (MAP1B) autoimmunity more commonly presents with a painless polyradiculoneuropathy [69•]." (PMID 36781586, 2023).
bladder tumor (1 paper, 2020). "Of these, CNS tumor has highest MAP1B expression; bladder tumor has moderate expression." (PMID 32182788, 2020).
breast tumor (1 paper, 2024). "However, CYR61, FLRT2, SLIT2, VNN1, MAP1B, MYLK, and TUBA1A gene expressions were high in normal adjacent tissue in comparison with those in breast tumor tissue." (PMID 39596804, 2024).
chronic obstructive pulmonary disease (1 paper, 2017). A chronic and progressive lung disorder characterized by the loss of elasticity of the bronchial tree and the air sacs, destruction of the air sacs wall, thickening of the bronchial wall, and mucous accumulation in the bronchial tree. "Tessema et.al reported that methylation of MAP1B promoter was more frequent in lung tumors with chronic obstructive pulmonary disease (COPD) than those without COPD." (PMID 28881838, 2017).
chronic pancreatitis (1 paper, 2025). A chronic inflammatory process causing damage and fibrosis of the pancreatic parenchyma. "Four genes (TNFRSF12A, MAP1B, EZR and YWHAZ) upregulated in donors with chronic pancreatitis were also upregulated in vimentin-positive α-cells in donors without diabetes or CF." (PMID 39836539, 2025).
cognitive decline (1 paper, 2026). "For example, the downregulation of NEFL, MAP1B, and GAP43—genes essential for axonal stability, cytoskeletal organization, and synaptic plasticity—may underlie the progressive cognitive decline and neurodevelopmental delay frequently reported in POLG‐related encephalopathies." (PMID 41355579, 2026).
colonic carcinoma (1 paper, 2023). "MAP1b, associated with modeling processes in the cytoskeleton and absent in colonic carcinoma primary tumors, was equally expressed in metastatic and normal liver tissue on PCR." (PMID 36831399, 2023).
coronary artery disease (1 paper, 2018). "However, CDKN2B-AS was involved in the pathogenesis of coronary artery disease by targeting miR-92a-3p through GATA2, MAP1B and ARG1 regulation." (PMID 29552296, 2018).
dementia with Lewy body (1 paper, 2023). "There have been several reports on the presence of MAP1B within Lewy bodies extracted from postmortem cortical samples obtained from individuals diagnosed with Lewy body dementia, and therefore, MAP1B may interact with α‐syn to form Lewy bodies." (PMID 38020716, 2023).
Hearing impairment (1 paper, 2020). A decreased magnitude of the sensory perception of sound. "The cosegregation of heterozygous mutations (p.1400S>G, p.923I>T, p.1838F>L) in the MAP1B gene with hearing impairment in these subjects of 3 Chinese pedigrees suggested that these MAP1B mutations are responsible for the development of hearing loss." (PMID 33268592, 2020). "In particular, Map1b+/– mice at the age of 4 weeks exhibited hearing impairment, evidenced by higher ABR thresholds than WT mice." (PMID 33268592, 2020).
hearing loss (1 paper, 2020). "We demonstrated that the dysfunctions of SGNs caused by MAP1B deficiency led to hearing loss." (PMID 33268592, 2020). "Therefore, our data demonstrate that dysfunctions of spiral ganglion neurons induced by MAP1B deficiency caused hearing loss." (PMID 33268592, 2020).
insulinomas (1 paper, 2017). "Differential expression of UCH-L1, MAP1B, MAP2, VCAN, CDK4 and PDX-1 was verified in more than 40 PNETs, including insulinomas and non-insulinomas by IHC but the expression of CaSR was only validated in 29 insulinomas." (PMID 28526880, 2017).
large cell lung carcinoma (1 paper, 2021). "Meanwhile, a 2.384-fold increase in MAP1B mRNA expression was observed in large cell lung carcinoma samples (p = 4E-3)." (PMID 34660263, 2021). "Besides, the Hou Lung dataset revealed a 3.136-fold increase in MAP1B mRNA expression in large cell lung carcinoma tissues (p = 9.06E-6)." (PMID 34660263, 2021).
lipoma (1 paper, 2024). A benign, usually painless, well-circumscribed lipomatous tumor composed of adipose tissue. "In addition to known RITA partners, such as RBP-J (recombination signal binding protein for immunoglobulin kappa J region) and LPP (lipoma-preferred partner), PRC1, NUMA1 (nuclear mitotic apparatus protein 1) and MAP1B (microtubule-associated protein 1B) were among the RITA interaction partners." (PMID 39839673, 2024).
male infertility (1 paper, 2024). The inability of the male to effect fertilization of an ovum after a specified period of unprotected intercourse. "Furthermore, the ICSI-associated DEGs MAP1B, HBA1, EPHX1, HBB, and HBG2 enriched in response-to-toxic-substance pathway are also interesting (FDR-corrected q-value < 0.05), considering that environmental exposures have been associated with male infertility in previous studies." (PMID 39702541, 2024).
metastatic cancers (1 paper, 2024). A carcinoma which has spread from the original site of growth to another anatomic site. "Taken together, these observations suggest that MAP1B is highly implicated in the metastasis of specific types of cancers, and its manipulation may provide a novel therapeutic strategy for metastatic cancers." (PMID 38353696, 2024).
metastatic disease (1 paper, 2020). "In our present results and using a published transcriptome dataset (GSE31684), we first found that MAP1B was significantly upregulated in UC and associated with more advanced pT status and metastatic disease in UBUC." (PMID 32182788, 2020).
microphthalmia (1 paper, 2020). Congenital or developmental anomaly in which the eyeballs are abnormally small. "Moreover, genetic inactivation of MAP1B led to developmental abnormalities in the mouse CNS, including microphthalmia, weaker visual acuity and delayed optic nerve myelinogenesis and axonal maturation." (PMID 32521826, 2020).
neuritis (1 paper, 2017). A neuropathy arising from inflammation of one or more nerves. "The interaction between MAP1B and PiT2 was enhanced in differentiated Neuro2A cells and abolishing the interaction decreased the length of neuritis." (PMID 29259219, 2017).
periventricular nodular heterotopia 9 (1 paper, 2022). "On June 22, 2020, periventricular nodular heterotopia 9 (OMIM 618918) caused by the MAP1B variant was registered as a new entry." (PMID 35346031, 2022).
prostate adenocarcinoma (1 paper, 2022). "Comparison of mRNA expression in prostate adenocarcinoma (Tumour, T = 492) versus normal prostate tissue (Normal, N = 152) showed a significant difference for microtubule-associated protein 1B (MAP1B)." (PMID 36614061, 2022).
retinal degeneration (1 paper, 2020). Degeneration of the retina. "MAP1B reduction causes Golgi fragmentation and ectopic vesicle transport due to decreased microtubule acetylation, and its heterozygous knockout mice exhibit retinal degeneration with photoreceptor loss." (PMID 31408169, 2020).
Rett syndrome (1 paper, 2020). A severe neurodevelopmental disorder affecting the central nervous system. "Downregulation of miR-146a-5p leads to an increase in dendritic microtubule-associated protein 1B (MAP1B) translation which can reduce synaptic transmission in neurons and this pathway is part of the pathogenesis of Rett syndrome." (PMID 32574550, 2020).
scrapie (1 paper, 2020). A fatal disease of the nervous system in sheep and goats, characterized by pruritus, debility, and locomotor incoordination. "Dendritic microtubule-associated protein 1B (MAP1B) is required for dendritic spine development, and the increased miR-146a expressed in the brains of scrapie model mice might target dendritic MAP1B protein and induce synaptic dysfunction." (PMID 32581706, 2020).
sensorineural hearing loss (1 paper, 2020). "Three novel heterozygous MAP1B mutations (c.4198A>G, p.1400S>G; c.2768T>C, p.923I>T; c.5512T>C, p.1838F>L) were cosegregated with autosomal dominant inheritance of nonsyndromic sensorineural hearing loss in 3 unrelated Chinese families." (PMID 33268592, 2020).
Sepsis (1 paper, 2025). Sepsis is defined as life-threatening organ dysfunction caused by a dysregulated host response to infection. "In sepsis, Microglia 1 exhibited strong upregulation of pro-inflammatory genes (e.g., GPNMB, CXCR4, HLA-DRB5) and downregulation of BBB-supportive genes (e.g., SPARCL1, MAP1B), indicating a highly reactive phenotype." (PMID 41030458, 2025).
small cell lung carcinoma (1 paper, 2021). Small cell lung cancer (SCLC) is a highly aggressive malignant neoplasm, accounting for 10-15% of lung cancer cases, characterized byrapid growth, and early metastasis. "Moreover, the MAP1B has been reported to be a new target in paraneoplastic neuropathy and has a high predictive value for small cell lung cancer." (PMID 34660263, 2021).
spinal muscular atrophy (1 paper, 2025). A motor neuron disease that affect the muscles, and characterized by muscle weakness and atrophy resulting from progressive degeneration and irreversible loss of the anterior horn cells in the spinal cord (i.e., lower motor neurons) and the brain stem nuclei. "However, despite MAP1B ́s role in cellular structural stability, MAP1B has been attributed regulatory function in morphology and physiology of synapses and is involved in the pathomechanisms of spinal muscular atrophy." (PMID 40681694, 2025).
type 2 diabetes (1 paper, 2023). "Furthermore, MAP1B is the first candidate susceptibility gene for type 2 diabetes." (PMID 37056668, 2023).
tumor (16 papers, 2008 to 2025). "In patients with UTUC, MAP1B overexpression was positively associated with synchronous multiple tumors, advanced pathological tumor stage, positive lymph node metastasis, the presence of vascular invasion, and an increased mitotic rate." (PMID 32182788, 2020). "For example, Ras-association domain family 1 isoform A (RASSF1A), a tumor suppressor whose inactivation is implicated in the development of many human cancers, interacts with MAP1B to influence microtubule dynamics in the cell cycle and is involved in the inhibition of cancer cell growth." (PMID 32182788, 2020). "However, in patients with UBUC, MAP1B overexpression was associated with advanced pathological tumor stage, positive lymph node metastasis, high histological tumor grade, the presence of vascular invasion, and an increased mitotic rate." (PMID 32182788, 2020). "We also propose the molecular mechanisms by which TNBC cells exploit MAP1B for tumor growth and invasion by preventing autophagic degradation of Tks5." (PMID 38353696, 2024). "In multivariate analysis, multifocal tumors, advanced pathological tumor stage, positive lymph node metastasis, high histological tumor grade, perineural invasion, and MAP1B expression were independently predictive for both DSS and MFS (all p < 0.05)." (PMID 32182788, 2020). "Using multivariate analysis, we confirmed that advanced pathological tumor stage, an increased mitotic rate, and MAP1B expression remained significant in predicting reduced DSS and MFS (all p < 0.05)." (PMID 32182788, 2020). "Among the genes included in the signature, MAP1B was prioritized for further functional investigation due to its relatively high hazard ratio in univariate Cox regression and previous reports implicating its role in neural development and tumor progression." (PMID 41208987, 2025). "LAMA2, MAP1B, and HIP1R were among the genes with higher mutation frequencies (8%, 6%, and 5%, respectively), suggesting these mutations play a crucial part in tumor initiation and progression, and these genes could be potential driver genes or therapeutic targets." (PMID 40589759, 2025). "It has been reported that MAP1B was remarkably overexpressed in BLCA tissues and positively correlated with tumor pathological tumor stage, grade, lymph node metastasis and vascular invasion, knockdown of MAP1B could reverse chemoresistance by interrupting the cell cycle." (PMID 36973787, 2023). "Through the Comparative Toxicogenomics Database—CTD database—among the 15 EMT genes described, four genes (MMP2, MAP1B, SNAI2, and WNT5A) were related to neoplasms and brain disorders, named neuronal EMT-related genes." (PMID 36553576, 2022). "Depleting MAP1B leads Tks5 to autophagic degradation and destabilizes invadopodia, resulting in reduced ECM degradation and impaired invasiveness, concomitant with decreased tumor cell growth." (PMID 38353696, 2024). "The influence of MAP1B and P4HB in tumor immune infiltration cannot be ignored." (PMID 35954405, 2022). "Except for fibroblasts, a total of 937 endothelial cells were also obtained, which were subclustered into five subsets, including extra-alveolar capillary ECs (Endo-C1; EDN1+), tumor ECs (Endo-C3; INSR+), and other ECs (Endo-C2, ICAM1+; Endo-C4, MAP1B+; Endo-C5, CXCR4+)." (PMID 36046337, 2022). "Functional enrichment (GSVA, GSEA), tumor microenvironment estimation (ESTIMATE, ssGSEA), drug sensitivity prediction (GDSC2), and in vitro experiments were performed to characterize the biological and therapeutic relevance of PRGS, with MAP1B selected for experimental validation." (PMID 41208987, 2025). "Moreover, the depletion of C19ORF5 or MAP1B did not prevent NORE1A's ability to suppress tumour cell growth." (PMID 18710533, 2008).